FBXO11 (F-box protein 11)
Description:
Substrate recognition component of a SCF (SKP1-CUL1-F-box protein) E3 ubiquitin-protein ligase complex which mediates the ubiquitination and subsequent proteasomal degradation of target proteins, such as DTL/CDT2, BCL6, SNAI1 and PRDM1/BLIMP1. The SCF(FBXO11) complex mediates ubiquitination and degradation of BCL6, thereby playing a role in the germinal center B-cells terminal differentiation toward memory B-cells and plasma cells. The SCF(FBXO11) complex also mediates ubiquitination and degradation of DTL, an important step for the regulation of TGF-beta signaling, cell migration and the timing of the cell-cycle progression and exit. The SCF(FBXO11) complex also catalyzes ubiquitination and degradation of GSK3B-phosphorylated SNAI1. Plays a role in the regulatiom of erythropoiesis but not myelopoiesis or megakaryopoiesis. Mechanistically, activates erythroid genes by mediating the degradation of BAHD1, a heterochromatin-associated protein that recruits corepressors to H3K27me3 marks. Participates in macrophage cell death and inflammation in response to bacterial toxins by regulating the expression of complement 5a receptor 1/C5AR1 and IL-1beta. Acts as a critical regulator to determine the level of MHC-II by mediating the recognition of degron at the P/S/T domain of CIITA leading to its ubiquitination and subsequent degradation via the proteasome. Participates in the antiviral repsonse by initiating the activation of TBK1-IRF3-IFN-I axis. Mediates the 'Lys-63'-linked ubiquitination of TRAF3 to strengthen the interaction between TRAF3 and TBK1.
Synonyms: FBX11; VIT1; UG063H01; UBR6; IDDFBA
Tractability: PROTAC: ubiquitination databases record sites on it; its protein half-life has been measured.
Gene: Protein-coding gene on chromosome 2 (47,789,316 to 47,906,507, reverse strand). Ensembl gene ENSG00000138081.
Subcellular location: Nucleus; Chromosome
Subcellular location (Human Protein Atlas): Nucleoli; Nucleoplasm
Pathways (Reactome):
Immune System: Antigen processing: Ubiquitination & Proteasome degradation
Metabolism of proteins: Neddylation
Gene Ontology:
Molecular function: protein binding; protein-arginine N-methyltransferase activity; ubiquitin-like ligase-substrate adaptor activity; ubiquitin-protein transferase activity; zinc ion binding
Biological process: negative regulation of epithelial to mesenchymal transition; proteasome-mediated ubiquitin-dependent protein catabolic process; protein ubiquitination; regulation of apoptotic process; SCF-dependent proteasomal ubiquitin-dependent protein catabolic process; ubiquitin-dependent protein catabolic process
Cellular component: chromosome; cytoplasm; nucleolus; nucleoplasm; nucleus; SCF ubiquitin ligase complex; cytosol; ubiquitin ligase complex
Genetic constraint (gnomAD): Loss-of-function variants: 8 observed, 67.11 expected, observed/expected ratio (o/e) 0.12, 90% interval 0.069 to 0.22. The synonymous counts are far from expectation, so gnomAD's model fits this gene poorly and the ratio says little. Missense variants: 533 observed, 862.57 expected, observed/expected ratio (o/e) 0.62, 90% interval 0.57 to 0.66. Synonymous variants: 377 observed, 287.2 expected, observed/expected ratio (o/e) 1.31, 90% interval 1.21 to 1.43.
Cancer hallmarks: invasion and metastasis (promotes); invasion and metastasis (suppresses); escaping programmed cell death (suppresses); proliferative signalling (promotes)
Homologues: Orthologues: chimpanzee FBXO11 (99% identical), macaque FBXO11 (99% identical), pig FBXO11 (99% identical), dog FBXO11 (99% identical), rat Fbxo11 (99% identical), guinea pig FBXO11 (93% identical), rabbit FBXO11 (91% identical), mouse Fbxo11 (91% identical), tropical clawed frog fbxo11 (90% identical), Drosophila melanogaster FBXO11 (66% identical), Caenorhabditis elegans dre-1 (54% identical), Caenorhabditis elegans fbxo-11.2 (32% identical). Paralogues in human: FBXO10 (21% identical).
Diseases named in the same sentence as FBXO11 in open-access papers:
FBXO11 is named in the same sentence as 71 diseases in open-access papers, as found by Europe PMC text mining. Sharing a sentence is not in itself a finding about the gene and the disease. The quoted sentences say what the papers report.
breast carcinoma (12 papers, 2018 to 2025). "Likewise, FBXO11 suppression is associated with increased breast cancer cell apoptosis." (PMID 35564499, 2022). "Recently, FBXO11 has been reported to be a major negative regulator of MHC class II through ubiquitin-dependent proteasomal degradation of CIITA in breast cancer." (PMID 39409891, 2024). "FBXO11 promotes breast cancer progression via ubiquitination and degradation of Snail family proteins." (PMID 34249081, 2021). "Mounting evidences have revealed the role of F-box proteins in regulating EMT in multiple types of tumors, including FBXW7 in lung cancer and gastric cancer, FBXO11 in breast cancer and gastric cancer, and FBXO45 in prostate cancer and PCa." (PMID 34249081, 2021). "Specifically, in breast cancer, FBXO11 inhibits metastatic progression by targeting the Snail protein for degradation and blocking Snail-induced EMT." (PMID 31159774, 2019). "It was reported that miR-621 overexpression promoted breast cancer chemosensitivity through targeting FBXO11." (PMID 30309377, 2018). "In addition, FBXO11 mediates the degradation of the EMT transcription factor Snail in breast cancer cells." (PMID 31159774, 2019). "Our previous study demonstrated that FBXO11 ubiquitinates and degrades Snail through the proteasome, thereby blocking Snail-induced EMT and inhibiting tumor metastasis in breast cancer." (PMID 39409891, 2024). "Taken together, these findings support the notion that FBXO11 has a strong oncogenic role in HCC and breast cancer." (PMID 31159774, 2019). "FBXO11 blocks SNAIL-induced EMT, tumor initiation, and metastasis in multiple breast cancer models." (PMID 38864622, 2024). "In breast cancer, apoptosis following paclitaxel treatments is boosted by miR-7-5p, miR-542-3p, miR-621, and miR-5195-3p via directly modulating BCL-2, survivin, F-box protein 11 (FBXO11), and eukaryotic translation initiation factor 4A2 (EIF4A2), respectively." (PMID 33066509, 2020).
diffuse large B-cell lymphoma (10 papers, 2015 to 2026). "Mutations in the FBXO11 substrate–binding CASH domains were previously identified in diffuse large B cell lymphoma, and multiple scattered mutations were reported in a rare FBXO11-related neurodevelopmental disorder." (PMID 41542766, 2026). "FBXO11 has been found to be mutated in multiple diffuse large B-cell lymphoma cell lines and this inactivation correlates with increased levels and stability of BCL6." (PMID 26471094, 2015). "In addition, FBXO11 mutations were observed in patients with splenic marginal zone lymphoma, diffuse large B cell lymphomas, and pancreatic cancer." (PMID 30999935, 2019). "While mutations in FBXO11 have been identified in diffuse, large B cell lymphoma (DLBCL) and Burkitt’s Lymphoma, these mutations predominantly occur in the substrate recognition sites on FBXO11: CASH domains from amino acids 418–837." (PMID 41542766, 2026). "FBXO11 gene silencing led to the development of diffuse large B-cell lymphoma (DLBCL) by targeting the degradation of Bcl-6, while FBXO11 inactivation resulted in abnormal germinal-centre formation." (PMID 31159774, 2019). "Bcl-6, a proto-oncogene overexpressed in diffuse large B-cell lymphoma (DLBCL), is targeted by FBXO11 for polyubiquitination and degradation." (PMID 30359271, 2018). "In conclusion we present a case of a boy with developmental delay resulting from a de novo germline 2p16.3 deletion including FBXO11 and MSH6, who developed a diffuse large B-cell lymphoma." (PMID 33811277, 2021). "According to the cBioPortal and COSMIC databases, FBXO11 alterations have been detected in various adult neoplasms, including colon cancer, lung cancer, ovarian cancer, and head and neck cancer, as well as in diffuse large B-cell lymphoma (DLBCL)." (PMID 33811277, 2021). "Biologically, the overexpression of FBXO11 inhibits cell proliferation and induces cell apoptosis by facilitating BCL-6 degradation in diffuse large B cell lymphoma cells." (PMID 30999935, 2019). "We describe a case of a boy with neurodevelopmental delay and a diffuse large B-cell lymphoma (DLBCL) in whom we discovered a germline de novo 2p16.3 deletion including MSH6 and part of the FBXO11 gene." (PMID 33811277, 2021).
otitis media (10 papers, 2009 to 2023). Inflammation of the anatomical structures of the middle ear, which is most often caused by an infectious process. "The Jeff mouse mutant carries a mutation in the F-box only 11 gene (Fbxo11) and heterozygous animals display conductive deafness due to the development of otitis media (OM)." (PMID 32117459, 2020). "Regardless, these studies, and ours, provide strong evidence that FBXO11 is associated with risk of otitis media." (PMID 28970529, 2017). "FBXO11 mutations in mice and humans are associated with ear inflammation due to otitis media." (PMID 36977592, 2023). "Recurrent infections and/or otitis media have been reported in several cases, which is notable as also a heterozygous Fbxo11 mouse model showed increased susceptibility to chronic otitis media, which may point to a role of FBXO11 in immune response." (PMID 34505148, 2022). "FBXO11 protein is expressed in middle ear pseudostratified epithelium of wild-type mice from embryonic day (E) 18.5 to P21, but the role of the Fbxo11Jf/+ mutation in otitis media pathogenesis remains unclear." (PMID 30898767, 2019). "FBXO11 is a candidate disease gene in human chronic otitis media with effusion and we report that a bulla cavitation defect initiates the pathogenesis of otitis media in the established mouse model Jeff (Fbxo11Jf/+)." (PMID 30898767, 2019). "Previous candidate gene studies associated a number of immune system genes with otitis media, which included TNF-α, IL-6, IL-10, Tlr4, surfactant, CD14, FcγRIIa, IFNγ, Eya4, p73, MyD88, Fas, E2f4, Plg, Fbxo11, and Evi1." (PMID 24466073, 2014). "Fbxo11 has since been shown to affect the TGF-β pathway and susceptibility to otitis media associated with mutations in this gene have been reported in humans." (PMID 21936904, 2011). "This indicates that there may be roles for FBXO11 in normal bulla development and homeostasis as well as in otitis media in Fbxo11Jf/+ mice." (PMID 30898767, 2019). "Both the TGIF1 and FBXO11 loci are thought to be involved in TGF-β signalling, which implies that TGF-β may be critical in the transition from acute to chronic middle ear inflammation, and could be a future target for molecular therapies." (PMID 28970529, 2017).
gastric cancer (9 papers, 2019 to 2025). A primary or metastatic malignant neoplasm involving the stomach. "miR-585 can interact with both linc01463 and FBXO11, indicating that linc01463 sequesters miR-585 and suppresses its activity, thereby indirectly upregulating FBXO11 expression in gastric cancer." (PMID 40534867, 2025). "In summary, linc01463 modulates the miR-585/FBXO11 axis, contributing to the progression of gastric cancer." (PMID 40534867, 2025). "Mechanistically, miR-585 can bind to linc01463 and FBXO11, suggesting that linc01436 sponges miR-585 and inhibit it, leading to indirect promotion of FBXO11 expression in gastric cancer." (PMID 35928868, 2022). "Taken together, linc01463 targets miR-585/FBXO11 axis and subsequently promotes progression of gastric cancer." (PMID 35928868, 2022). "Moreover, gene FBXO11, XPO1, SLC3A2, and APC, whose mutation detections may be affected by various tumor purities in gastric cancer, were closely related with cancer occurrence and development." (PMID 33425983, 2020). "Recent studies have also focused on tumor promotion in gastric cancer and potential targets for treatment, including MGST1, TTPAL, FBXO11, and IL2RG." (PMID 40186098, 2025). "Mechanistically, the EMT process is dramatically stimulated by FBXO11 through the PI3K/Akt signaling pathway, which leads to the promotion of gastric cancer cell proliferation and metastasis." (PMID 30999935, 2019).
lung carcinoma (7 papers, 2021 to 2025). "To explore the role of FBXO11 in the modulation of the migration and invasion of lung cancer cells, we examined the expression of genes that regulate EMT in A549 and H1299 cells." (PMID 39409891, 2024). "Collectively, our study demonstrates that FBXO11 modulates EMT by mediating the stability of ZEB1 in lung cancer cells." (PMID 39409891, 2024). "Loss of FBXO11 increases ZEB1 levels, enhancing the invasiveness of lung cancer cells, while its overexpression reduces ZEB1 and suppresses invasion." (PMID 39409891, 2024). "Here, we speculated that FBXO11 might have a similar regulatory effect on ZEB1 in lung cancer cells." (PMID 39409891, 2024). "Taken together, we confirm that EMT transcription factor ZEB1 plays a major role in the invasion and metastasis of lung cancer and that FBXO11 can ubiquitinate ZEB1 and be recognized by the proteasome for degradation, thereby inhibiting the invasion and metastasis of lung cancer cells." (PMID 39409891, 2024). "FBXO11 was also found to inhibit lung cancer cell migration and invasion in vivo in xenograft mice." (PMID 39409891, 2024). "In a word, lincRNA GATA6-AS1 might regulate miR-324-5p/FBXO11 axis and facilitated lung cancer development." (PMID 35928868, 2022). "Using GEPIA, we performed gene correlation analysis using Transcripts Per Million (TPM) for lung cancer data in the TCGA/GTEx database and found that the ZEB1 gene was positively correlated with the FBXO11 gene." (PMID 39409891, 2024). "This study systematically investigated the molecular mechanisms through which E3 ubiquitin ligase FBXO11 mediates the ubiquitination and degradation of ZEB1, thereby regulating the invasive metastasis of lung cancer cells." (PMID 39409891, 2024). "Increased abundance of ARRB1, as well as FBXO11, LYZ, RPS6KB1, and SYNGR2 have comparable oncogenic effects in hepatocellular carcinoma, and MGST1 and RPS6KB1 have noted oncogenic roles in various lung cancers." (PMID 40186098, 2025). "Similarly, GATA6-AS1 overexpression elevates the expression of FBXO11 and SP1 by acting as a sponge for miR-324-5p, thereby enhancing the invasion and proliferation of lung cancer cells." (PMID 40534867, 2025). "Moreover, GATA6-AS1 overexpression increased the expression of FBXO11 and SP1 via sponging miR-324-5p, contributing to enhancement of invasion and proliferation in lung cancer cells." (PMID 35928868, 2022).
lymphoma (7 papers, 2015 to 2022). A malignant (clonal) proliferation of B- lymphocytes or T- lymphocytes which involves the lymph nodes, bone marrow and/or extranodal sites. "Since FBXO11 has been demonstrated to mediate ubiquitination of BCL6 in lymphoma, it is reasonable to attempt to rescue FBXO11 loss through inhibition of proteasomal degradation." (PMID 33024076, 2020). "FBXO11 has been found to target BCL6 for ubiquitin-mediated degradation and mutations in FBXO11 associated with lymphoma." (PMID 31042473, 2019). "Biallelic deletion and silencing of FBXO11 among lymphoma cell lines occurred uniquely in FARAGE along with raised BCL6 expression." (PMID 26599546, 2015). "Therefore, assessment of larger cohorts of individuals with constitutional FBXO11 aberrations is required to establish whether the incidence of lymphoma is indeed enriched inthese individuals." (PMID 33811277, 2021). "FBXO10 and FBXO11 bind to BCL2 and BCL6, respectively, resulting in their ubiquitination and promoting their degradation, thereby regulating the levels of BCL2 and BCL6 proteins in lymphoma cells." (PMID 36644760, 2022).
chronic otitis media (6 papers, 2017 to 2024). Chronic form of otitis media (disease). "For example, the Jeff mouse model of chronic otitis media harbours a FBXO11 mutation, which interferes with TGF-βsignalling." (PMID 31159774, 2019). "In conclusion, by comparing the phenotype of mice carrying a null mutation in the Fbxo11 gene with the well-characterized chronic otitis media model, Jeff, we have demonstrated that the Jeff mutation is both a loss-of-function mutation and a gain-of-function mutation." (PMID 32508883, 2020).
prostate carcinoma (6 papers, 2017 to 2025). A carcinoma that arises from epithelial cells of the prostate gland. "In summary, this study unveils the association between NDR1 and prostate cancer, shedding light on its regulatory mechanism over β-catenin via a phosphorylation-dependent ubiquitination pathway mediated by FBXO11." (PMID 39309441, 2024). "MiR-21 directly inhibits the expression of FBXO11 in melanoma, prostate cancer, and glioma, thereby promoting tumorigenesis." (PMID 40534867, 2025). "This study delves into NDR1-dependent phosphorylation's impact on β-catenin via FBXO11, an E3 ubiquitin ligase, in prostate cancer cells." (PMID 39309441, 2024). "Additionally, studies have demonstrated that NDR1/FBXO11 enhances phosphorylation-mediated ubiquitination of β-catenin, thereby inhibiting metastasis in prostate cancer." (PMID 40771930, 2025). "Consequently, NDR1 and FBXO11 collaboratively regulate β-catenin activity in prostate cancer cells through a mechanism of dual phosphorylation-driven ubiquitination, potentially suppressing EMT." (PMID 40771930, 2025). "Thus, NDR1 and FBXO11 jointly regulate β-catenin activity in prostate cancer cells through dual phosphorylation-driven ubiquitination, potentially suppressing EMT." (PMID 39309441, 2024). "H3K27me3 enrichment on the FBXO11 promoter may mediate the repression of this gene in prostate cancer." (PMID 28403887, 2017). "Further investigations reveal that NDR1 phosphorylates FBXO11 at Ser187, enhancing its ubiquitination of β-catenin, which regulates EMT and prostate cancer progression." (PMID 39309441, 2024). "In summary, these findings confirm that NDR1 phosphorylates FBXO11 at Ser187, and this phosphorylation-mediated FBXO11 ubiquitination of β-catenin regulates the EMT and prostate cancer progression." (PMID 39309441, 2024). "Reduced NDR1 expression inhibited FBXO11 and β-catenin phosphorylation, diminishing β-catenin and JNK2 ubiquitination, promoting EMT and enhancing prostate cancer cell metastasis." (PMID 39309441, 2024). "Immunohistochemistry of prostate cancer lung metastatic lesions from the nude mice confirmed that NDR1 and FBXO11 overexpression suppressed the expression of β-catenin." (PMID 39309441, 2024).
acute myeloid leukemia (5 papers, 2021 to 2026). Acute myeloid leukemia (AML) is a group of neoplasms arising from precursor cells committed to the myeloid cell-line differentiation. "Recently, FBXO11 was also identified as a potential tumor suppressor in myelodysplastic syndrome and secondary acute myeloid leukemia." (PMID 33811277, 2021). "In acute myeloid leukaemia (AML), the CtBP complex transcriptionally represses MHC‐II genes, while the E3 ubiquitin ligase complex component FBXO11 promotes degradation of CIITA." (PMID 40673641, 2025).